CBX6 (chromobox 6)
Diseases named in the same sentence as CBX6 in open-access papers (continued):
Sharing a sentence is not in itself a finding about the gene and the disease.
rectal cancer (2 papers, 2020 to 2025). A primary or metastatic malignant neoplasm that affects the rectum. "High mRNA expression of CBX6 was associated with short overall survival in rectal cancer patients." (PMID 40893943, 2025). "High CBX5 (HR = 6.27, p = 0.039) and CBX6 (HR = 4.27, p = 0.0037) mRNA expression was significantly correlated with short OS in rectal cancer patients." (PMID 33014884, 2020). "In rectal cancer, CBX6 expression was positively correlated with the infiltration of CD4+ T cells, macrophages, and dendritic cells." (PMID 33014884, 2020). "Similarly, CBX6 showed the same characteristics in patients with rectal cancer, although its expression was increased in tumor tissues compared to normal tissues." (PMID 33014884, 2020).
acute myeloid leukemia (1 paper, 2018). Acute myeloid leukemia (AML) is a group of neoplasms arising from precursor cells committed to the myeloid cell-line differentiation. "In particular, high levels of BMI1, an oncogene highly expressed in acute myeloid leukemia and in advanced phases of CML, were connected to a poorer outcome, whereas on the other side a high expression of CBX6 and CBX7 played a favorable role." (PMID 30574454, 2018). "In acute myeloid leukemia, BMI1 is over-expressed, while other genes from the same family, such as CBX6 and CBX7, are down-regulated." (PMID 30574454, 2018).
breast adenocarcinoma (1 paper, 2019). "Next, the expression of CBX6 was assessed by qRT-PCR and by Western blotting using the antibody (Millipore 09-030) in a human non-tumorigenic epithelial cell line, MCF-10A, and two human breast adenocarcinoma cell lines, MCF-7 and MDA-MB-231." (PMID 30655550, 2019).
cervical cancer (1 paper, 2025). A primary or metastatic malignant neoplasm involving the cervix. "We found that CBX2, CBX4, and CBX8 presented notably increased expression, whereas PHC2, CBX6, and CBX7 presented decreased expression in cervical cancers." (PMID 39793896, 2025).
colon cancer (1 paper, 2020). "In colon cancer, CBX6 expression was shown to have a positive relation with the infiltration of the all immune cell types except for B cells." (PMID 33014884, 2020).
colorectal cancer (1 paper, 2025). A primary or metastatic malignant neoplasm that affects the colon or rectum. "It suggests a tumor-suppressive role for CBX6 in colorectal cancer, particularly in COAD." (PMID 40806514, 2025).
diffuse gastric adenocarcinoma (1 paper, 2020). An adenocarcinoma arising from the stomach. "Chen's gastric dataset revealed that CBX6 was upregulated in diffuse gastric adenocarcinoma (fold − change = 1.758 and P = 8.38E − 05)." (PMID 33344640, 2020).
endometrial tumors (1 paper, 2022). "As for CBX1 and CBX2—we observed positive association with cancer stemness in liver, lung and endometrial tumors, while CBX4, CBX5, CBX6, and CBX8 exhibit rather weak correlation with cancer stemness in a tumor-specific manner." (PMID 36361869, 2022).
gastric cancer (1 paper, 2022). A primary or metastatic malignant neoplasm involving the stomach. "The mRNA and protein expression levels of CBX2/3 in gastric cancer tissues were significantly higher than in normal tissues, whereas CBX6/7 were down-regulated in gastric cancer." (PMID 35969177, 2022).
leiomyosarcoma (1 paper, 2021). An uncommon, aggressive malignant smooth muscle neoplasm, usually occurring in post-menopausal women. "The expression levels of CBX6/8 in leiomyosarcoma (Barretina sarcoma database) and synovial sarcoma (Detwiller sarcoma database) were raised by 2.068- and 5.159-fold, respectively." (PMID 34046352, 2021).
lymph node metastasis (1 paper, 2020).
neuroendocrine tumor (1 paper, 2015). "In addition, overabundance of CBX6 and CBX8 transcripts was also observed in neuroendocrine tumor lines (P < 0.05, Mann-Whitney U test), consistent with our previous findings." (PMID 25859291, 2015).
osteosarcoma (1 paper, 2020). A usually aggressive malignant bone-forming mesenchymal neoplasm, predominantly affecting adolescents and young adults. "We found that CBX4 and CBX8, but not CBX2 or CBX6, was overexpressed in all 16 osteosarcoma tissues compared with the 4 normal tissues." (PMID 32111827, 2020). "In addition, depletion of other CBX family members, such as CBX2 and CBX6, or PRC1 core subunits, Ring1a and Ring1b, did not consistently show to affect the mRNA level of Runx2 in these osteosarcoma cell lines." (PMID 32111827, 2020).
pleural mesothelioma (1 paper, 2020). A neoplasm that arises from the mesothelial cells of the pleura. "Benign pleural mesothelioma also showed nuclear staining of CBX6 in the majority of the tumor cells (1 case)." (PMID 33028834, 2020).
renal cell carcinoma (1 paper, 2022). "In this study, we performed bioinformatic analysis to show that CBX7 and CBX6 functioned as protective factors with hazard ratios (HRs) less than 1 but CBX8 and CBX4 functioned as risk factors with HRs greater than 1 in renal cell carcinoma." (PMID 35342353, 2022).
sarcoma (1 paper, 2021). A usually aggressive malignant neoplasm of the soft tissue or bone. "In contrast, the mRNA expression levels of CBX6/7 in sarcoma were lower than those in normal tissues." (PMID 34046352, 2021). "Similarly, our present study suggested that higher expression levels of CBX6 were related to DFS in patients with sarcoma." (PMID 34046352, 2021).
tumor (36 papers, 2013 to 2026). "This indicates, that high levels of NT5E promoting miRNAs such as miR-224 or low expression of NT5E repressor such as CBX6/CNOT6L or NFACT3 are linked to progressive tumor disease reflected by shorter survival time." (PMID 37409119, 2023). "For both assessed RCC subtypes, these three CBXs presented a similar profile: CBX3/6/7 showed the highest rates of genetic alteration, CBX3 mRNA level was upregulated, CBX6/7 associated with tumor stage, and CBX7 also associated with better prognosis." (PMID 36292141, 2022). "In addition, decreased expression levels of CBX6/7 were associated with tumor stage for both RCC subtypes." (PMID 36292141, 2022). "In addition, the upregulated expression of CBX2/3/8 and downregulation of CBX6/7 were discovered to be associated with the tumor grade." (PMID 35210369, 2022). "Mechanistically, CBX6 promotes tumor growth through the S100A9/NF-κB/MAPK signaling pathway and contributes to metastasis of HCC cell lines and in vivo via transcription factors such as Snail and Zeb1 that mediate EMT." (PMID 40175347, 2025). "In this tumor, CBX6 is overexpressed and correlates with poor prognosis and increased tumor proliferation." (PMID 40175347, 2025). "In summary, in hematopoiesis, CBX2, CBX7, and CBX8 have oncogenic roles, whereas CBX4 and CBX6 function as tumor suppressors." (PMID 38426219, 2024). "Our results revealed higher expression of the CD276 and NMB proteins in tumor than in normal tissues, whereas CBX6 was only highly expressed in normal intestinal mucosal tissues." (PMID 37428291, 2023). "We analyzed the gene mutations of individuals with high and low expression of CBX6 and CBX7, evaluated immune cell infiltration by different immune algorithms in tumor tissue, and then verified the immune infiltration results." (PMID 37189494, 2023). "When tumor tissue exhibited low CBX6 expression, the infiltration of regulatory T cells (Tregs) (labelled by CD25) was markedly inhibited in the tumor center." (PMID 37189494, 2023). "To address the putative roles of Cbx6, Trib3, and Etv4 as downstream effectors of the tumor promoting effect of Kdm5c KD, we assessed the consequences of KD of either of them in combination with Kdm5c KD." (PMID 36631623, 2023). "We demonstrated that the tumor suppressive is mediated by both positively and negatively acting downstream effectors, including CBX6, TRIB3, ETV4 and FOS/JUN, where the first two also affect the differentiation status of Lp30 AML." (PMID 36631623, 2023). "The high expressions of the CBX family (including CBX2, CBX3, CBX5, and CBX6) in tumor tissues were related to the worse OS of DLBCL patients, whereas high expression of CBX1 was correlated with better prognosis of patients." (PMID 37430195, 2023). "In contrast, some subunits of PRC1 have also been reported to have tumor-suppressive roles such as CBX6 and PCGF2 in breast cancer." (PMID 36076977, 2022). "Otherwise, in the pRCC subtype, CBX2, CBX3, CBX7, and CBX8 were deregulated, and CBX2, CBX6, and CBX7 were associated with the tumor stage." (PMID 36292141, 2022). "Although without a net trend, the mRNA expression distribution of CBX1 in clear cell subtypes and CBX6 in both subtypes were significantly different among tumor stages." (PMID 36292141, 2022). "Although expression of CBX6/7 proteins were significantly upregulated in tumor tissues, its mRNA levels were almost similar between tumor and normal tissues based on the TCGA database." (PMID 35677563, 2022). "The highest mRNA levels of CBX3/8 were observed in tumor grade IV, whereas the highest mRNA levels of CBX6/7 were detected in tumor grade II." (PMID 35210369, 2022). "Our findings supported a different potential involvement of CBX6 in ccRCC and pRCC, and a similar tumor suppressive role for CBX7 in both assessed RCC subtypes." (PMID 36292141, 2022).
tumor (continued). "The results exhibited that the mRNA expression of CBX2/3/8 tended to be higher as tumor grade increased, whereas the mRNA expression of CBX6/7 tended to be lower with increasing tumor grade." (PMID 35210369, 2022). "Statistically, the mRNA expression of CBX2/3/8 tended to be higher as tumor grade increased, whereas the mRNA expression of CBX6/7 tended to be lower with increasing tumor grade." (PMID 35210369, 2022). "The elevated expression of CBX6 has been reported in HCC tissues and cell lines; CBX6 was also correlated with a larger tumor size (≥5 cm; p = 0.011)." (PMID 34046352, 2021). "In our study, CBX6 and CBX7 were favorable prognostic factors for ccRCC, and low CBX6 and CBX7 expression was positively associated with advanced cancer stage and tumor grade in ccRCC patients." (PMID 34395271, 2021). "In the present study, we demonstrated that CBX6 expression is increased in HCC cells and tumor tissues and that increased CBX6 expression is associated with poor outcomes in a large HCC cohort." (PMID 28122351, 2017). "CBX6 knockdown tumors (HCCLM3- CBX6i) showed significantly decreased tumor growth compared with control tumors (HCCLM3-NC), based on our measurements of tumor volume and weight." (PMID 28122351, 2017). "The staining intensity of the CBX6 protein in the tumor group was stronger than that in the peri-tumor group." (PMID 28122351, 2017). "We performed similar assessments of xenograft tumor formation in nude mice using CBX6 knockdown cells and the appropriate control cells." (PMID 28122351, 2017). "CBX6 may act as a tumor suppressor in chronic myeloid leukemia (CML), as its expression levels are low in untreated CML patients but increase during treatment with tyrosine kinase inhibitors (TKIs) used to manage the disease." (PMID 40175347, 2025). "Conversely, CBX6 consistently exhibited significant downregulation in tumor tissues." (PMID 40806514, 2025). "However, CBX6/7 mRNA expression was significantly lowered in tumor samples, which was consistent with prior findings." (PMID 37189494, 2023). "We presumed that CBX6 might regulate the populations of activated dendritic cells and activated mast cells in the tumor immune microenvironment, in turn affecting the development of tumors in elderly patients with CRC." (PMID 37428291, 2023). "We inferred that the mechanism underlying the regulation of activated dendritic cells and mast cells by CBX6 might play a crucial role in tumor development and prognosis of elderly patients with CRC." (PMID 37428291, 2023). "For EC, CBX3 and CBX6 were significantly overexpressed in tumor tissues compared to normal tissues." (PMID 36140750, 2022). "CBX1, CBX6, and CBX7 were also significantly associated with the tumor stage." (PMID 36292141, 2022). "Our results are consistent with the tumor suppression effects of CBX6 and CBX7." (PMID 34395271, 2021). "For instance, in many cancers CBX2/CBX8 are oncogenic while CBX6/CBX7 are tumor suppressive." (PMID 34617019, 2021). "The relevance of CBX6 in other tumor types and other cellular contexts must be further studied." (PMID 33028834, 2020). "Moreover, our study inferred that the mechanism underlying the regulation of activated dendritic cells and activated mast cells by CBX6 might playa crucial role in tumor development and prognosis in elderly patients with CRC." (PMID 37428291, 2023). "CBX6 may contribute to a poor prognosis in patients by inhibiting M1 polarization and promoting Treg recruitment in the tumor microenvironment, while CBX7 may contribute to a better prognosis in patients by increasing resting mast cell numbers and decreasing macrophage M0 content." (PMID 37189494, 2023). "Moreover, CBX6 expression was dramatically elevated in tumor tissues of HCC patients (P < 0.01)." (PMID 34381502, 2021). "In contrast, CBX6 displays a consistent downregulation across both CRC cell lines and tumor samples." (PMID 40806514, 2025).
tumor (continued). "Analysis revealed elevated expression of CBX2/3/5/8 and reduced expression of CBX6/7 in GBM, with correlations to tumor grade and recurrence." (PMID 40565099, 2025). "Overall, siRNA-mediated knockdown of CBX6, CNOT6L, and SRSF4 consistently enhanced NT5E surface levels in various human tumor cell lines." (PMID 37409119, 2023). "The expression of CBX genes differs across solid tumors and for CBX1, CBX2, CBX3, CBX4, CBX5, and CBX8 is predominantly upregulated, while for CBX6 and CBX7 is mostly downregulated in tumor tissues." (PMID 36361869, 2022). "Chromobox 6 (CBX6) is a subunit of PRC1 that mediates epigenetic gene repression and acts as an oncogene or tumor suppressor in a cancer type-dependent manner." (PMID 34572485, 2021). "Evidently, various reports have shown the elevated expression of USP22, CBX6, NRAGE, ACTL6, and CHMP4B genes correlate with larger tumor size, advanced tumor stages, poor prognosis and short survival time of patients in LIHC." (PMID 31490960, 2019). "Chromobox 6 (CBX6) is a subunit of Polycomb Repressive Complex 1 (PRC1) that mediates epigenetic gene repression and acts as an oncogene or tumor suppressor in a cancer type-dependent manner." (PMID 30655550, 2019). "Frequent up-regulation of CBX6 had been found in HCC tissues and HCC cell lines and that CBX6 expression was significantly related with tumor sizes and multiple tumors." (PMID 30481161, 2018). "In this study, we found that CBX6 was frequently up-regulated in HCC clinical samples and HCC cell lines and that CBX6 expression was significantly correlated with larger tumor sizes (≥ 5 cm, p = 0.011) and multiple tumors (n ≥ 2, p = 0.018)." (PMID 28122351, 2017). "Subgroup analysis revealed that among patients with a tumor size < 5 cm (140 patients), differences in RFS and OS still existed between the high and low CBX6 expression groups (p < 0.001)." (PMID 28122351, 2017). "Here, we show that silencing CBX6 in GBM cells promotes proliferation, migration, and invasion, while its overexpression yields the opposite effects, indicating its role as a negative regulator of tumor aggressiveness." (PMID 41883712, 2026). "For example, CBX4 and CBX6 are tumor suppressors in hematopoietic cells and therefore do not qualify as drug targets in leukemia." (PMID 38426219, 2024). "This may be because the baseline expression of CBX6/7 in normal tissues was already very low, so it is hard to detect lower CBX6/7 expression in GBM tumor tissues." (PMID 35210369, 2022). "Among them, the CBX4, CBX6, and CBX7 proteins have dual roles as oncogenic and tumor suppressors." (PMID 36076977, 2022). "As the tumor progressed, patients with more advanced tumor grades tended to express higher mRNA expression of CBX3 and CBX4 but lower mRNA expression of CBX1, CBX5, CBX6, and CBX7." (PMID 34395271, 2021). "The present study suggested that CBX6 and CBX7 could function as both oncogenes and tumor suppressors, depending on the tumor type and cellular context." (PMID 34395271, 2021). "Similarly, in our study, higher mRNA expression of CBX6 was found in HCC tissues compared to normal tissues, and was significantly related with patients’ individual cancer stages, tumor grades." (PMID 30481161, 2018). "To determine the protein expression patterns of CBX6 in the HCC clinical samples, we next performed immunohistochemistry (IHC) forCBX6 expression using HCC tissue microarrays (TMAs) containing 313 HCC samples and paired peri-tumor samples." (PMID 28122351, 2017). "CBX6/7 significantly correlates with immune cell infiltrations, particularly CD4+ T cells and macrophages, indicating that CBXs may also reveal immune status, hence regulating tumor status." (PMID 35969177, 2022). "In conclusion, our results represent the first evidence that CBX6 contributes to tumor progression and indicate that the protein may serve as a novel prognostic biomarker for HCC and as a therapeutic target in the treatment of the disease." (PMID 28122351, 2017).
tumor (continued). "Our qPCR results showed that relative CBX6 mRNA expression levels were significantly higher in the tumor tissue samples than the adjacent non-tumor tissue samples, as 84% (42/50) of the HCC tissue specimens showed a higher CBX6 mRNA expression level than their matched non-tumor counterparts." (PMID 28122351, 2017). "Understanding the functional significance of the reciprocal expression pattern of CBX8 relative to CBX6 and CBX7 in GBMs might eventually leads to the development of compounds targeting the chromodomain of a specific CBX protein which potentially have anti-tumor efficacy." (PMID 24260522, 2013). "Although CBX6 has not been reported to regulate hematopoietic cell fate decisions, both CBX6 and CBX7 are suggested to be tumor suppressors in chronic myeloid leukemia (CML)." (PMID 38426219, 2024).